PDE6D (phosphodiesterase 6D)
Description:
Promotes the release of prenylated target proteins from cellular membranes. Modulates the activity of prenylated or palmitoylated Ras family members by regulating their subcellular location. Required for normal ciliary targeting of farnesylated target proteins, such as INPP5E. Required for RAB28 localization to the cone cell outer segments in the retina (By similarity). Modulates the subcellular location of target proteins by acting as a GTP specific dissociation inhibitor (GDI) (By similarity). Increases the affinity of ARL3 for GTP by several orders of magnitude. Stabilizes ARL3-GTP by decreasing the nucleotide dissociation rate (By similarity).
Synonyms: PDED; JBTS22
Tractability: Small molecule: an approved drug acts on it; a structure with a bound ligand is known; a high-quality ligand is known; it has a high-quality binding pocket; it belongs to a druggable protein family. Antibody: UniProt places it where antibodies can reach, with high confidence. PROTAC: it is named in the literature on targeted protein degradation; ubiquitination databases record sites on it; its protein half-life has been measured; a small molecule that binds it is known.
Target class: Phosphodiesterase 6D; Phosphodiesterase 6; Enzyme; Phosphodiesterase
Gene: Protein-coding gene on chromosome 2 (231,732,354 to 231,786,272, reverse strand). Ensembl gene ENSG00000156973.
Subcellular location: Cytoplasm, cytosol; Cytoplasmic vesicle membrane; Cytoplasm, cytoskeleton, cilium basal body
Subcellular location (Human Protein Atlas): Vesicles
Pathways (Reactome):
Organelle biogenesis and maintenance: ARL13B-mediated ciliary trafficking of INPP5E
Signal Transduction: RAS processing
Gene Ontology:
Molecular function: protein binding; small GTPase binding; GTPase inhibitor activity
Biological process: visual perception; sensory perception of light stimulus
Cellular component: cytoplasmic vesicle; cytoplasmic vesicle membrane; cytosol; cilium; cytoplasm
Genetic constraint (gnomAD): Loss-of-function variants: 4 observed, 8.91 expected, observed/expected ratio (o/e) 0.45, 90% interval 0.22 to 1.03. That is too few expected variants to judge how well the gene tolerates losing a copy. Missense variants: 62 observed, 72.33 expected, observed/expected ratio (o/e) 0.86, 90% interval 0.7 to 1.06. Synonymous variants: 27 observed, 25.95 expected, observed/expected ratio (o/e) 1.04, 90% interval 0.77 to 1.43.
Gene-disease validity (ClinGen):
ClinGen rates the evidence that PDE6D causes each of these diseases.
ciliopathy (autosomal recessive): Moderate. A genetic disorder of the cellular cilia or the cilia anchoring structures, the basal bodies, or of ciliary function.
Homologues: Orthologues: chimpanzee PDE6D (100% identical), dog PDE6D (99% identical), pig PDE6D (99% identical), mouse Pde6d (98% identical), guinea pig PDE6D (97% identical), rat Pde6d (97% identical), zebrafish pde6d (91% identical), tropical clawed frog pde6d (89% identical), macaque PDE6D (85% identical), Caenorhabditis elegans pdl-1 (69% identical), Drosophila melanogaster PrBP (61% identical).